H19 (H19 imprinted maternally expressed transcript)
Synonyms: D11S813E; ASM; ASM1; NCRNA00008; LINC00008; MIR675HG; GMRSP; BWS; WT2
Gene: Long non-coding RNA gene on chromosome 11 (1,995,165 to 2,004,552, reverse strand). Ensembl gene ENSG00000130600.
Diseases named in the same sentence as H19 in open-access papers:
H19 is named in the same sentence as 446 diseases in open-access papers, as found by Europe PMC text mining. Sharing a sentence is not in itself a finding about the gene and the disease. The quoted sentences say what the papers report.
breast cancer (288 papers, 2009 to 2026). A primary or metastatic malignant neoplasm involving the breast. "H19, one of the earliest lncRNAs linked to breast cancer, regulates the H19/IGF2 imprinting axis and is frequently upregulated across multiple tumor types." (PMID 41516015, 2025). "On the other hand, the H19 SNP rs3741219 variant has been linked to an increased risk of diseases such as breast cancer." (PMID 39898248, 2025). "For instance, in breast cancer tissues, elevated levels of lincRNA H19 are linked to more advanced disease stages and poorer prognoses." (PMID 39997609, 2025). "The findings confirm that certain H19 SNPs are associated with heightened breast cancer risk and that the expression profiles of related genetic markers can significantly influence prognosis and treatment response." (PMID 39267845, 2024). "Circulating exosomal lncRNA H19 has been described as a potential biomarker with diagnostic and prognostic value in gastric cancer (GC) and breast cancer." (PMID 39594687, 2024). "In another study, EVs secreted by hypoxia-induced tumor-associated fibroblasts contain lncRNA H19, which can be delivered to recipient breast cancer cells and cause a reduction of miR-497 levels in a DNMT1-dependent manner." (PMID 39585046, 2024). "This suggests that finding and verifying the H19 polymorphisms that are closely related to breast cancer is of great significance." (PMID 39267845, 2024). "This study focuses on the role of H19 gene polymorphisms, investigating their impact on breast cancer susceptibility, clinical outcomes, and response to treatment." (PMID 39267845, 2024). "This study explored the role of H19 polymorphisms in breast cancer, assessing their impact on risk, clinical outcomes, treatment responses, and prognosis via SNP analysis." (PMID 39267845, 2024). "Frequency distribution of H19 genotypes and their associations with the risk of developing breast cancer." (PMID 39267845, 2024). "The study underscores the critical roles of LincRNA H19 and miR-675 as prognostic biomarkers in breast cancer, with their overexpression associated with disease progression and adverse outcomes." (PMID 39267845, 2024). "Upregulation of lncRNA H19 was reported to associate with increased ERα expression in endocrine therapy-resistant breast cancer patients." (PMID 36672487, 2023). "In Tamoxifen-treated or Fulvestrant-treated estrogen receptor-alpha positive (ERα+) breast cancer tumors, high H19 expression is associated with increased drug resistance." (PMID 36246634, 2022). "In clinical studies of breast cancer patients, hormone negativity, tumor size, and nodal status are all linked to high H19 expression." (PMID 35864503, 2022). "Current evidence suggests that H19 is overexpressed in prostate cancer, glioblastoma, and breast cancer and is associated with cancer progression." (PMID 36160000, 2022). "Another well-known cancer-associated lncRNA, H19, a maternally inherited imprinted gene, is reported to be overexpressed in breast cancer, and associated with poor prognosis in breast cancer patients, especially in the triple-negative molecular subtype." (PMID 34946977, 2021). "One of the representative lncRNAs, H19, is recognized as a cancer biomarker and is associated with the occurrence of esophageal cancer, colorectal cancer, liver cancer, breast cancer, bladder cancer, and stomach cancer." (PMID 33680956, 2020). "Long non-coding RNA H19 (lncRNA H19) has been implicated in tumorigenesis and metastasis of breast cancer through regulating epithelial to mesenchymal transition (EMT); however, the underlying mechanisms remain elusive." (PMID 32514245, 2020). "In brief, serum exosomal H19 can serve as a non‐invasive diagnostic and prognostic biomarker for patients with breast cancer or bladder cancer." (PMID 32924276, 2020). "In breast cancer, 91H lncRNA prevents DNA methylation on the maternal allele at the H19/IGF2 locus, and thereby increases aggressive phenotype of breast cancer cells." (PMID 32929060, 2020).
breast cancer (continued). "It was also shown that the polymorphic site of rs217727 on H19 was associated with the risk of breast cancer (OR = 0.79; 95%CI = 0.55 − 0.97)." (PMID 32337223, 2020). "High expression levels of H19 increase the drug resistance of breast cancer cells and is associated with poor prognosis within patients with breast cancer." (PMID 32345117, 2020). "For example, lncRNA H19, an imprinted gene is associated with breast cancer cell clonogenicity, migration and mammosphere-forming ability." (PMID 32324747, 2020). "In cancer, H19 is frequently overexpressed and it is associated with many aspects of cancer development, including breast cancer." (PMID 32345117, 2020). "Lnc-ARSR causes sunitinib resistance in RCC, lnc-H19 promotes resistance to fulvestrant and tamoxifen in breast cancer, and lnc-NEAT1 enhances resistance to sorafenib in HCC." (PMID 32219093, 2020). "In breast cancer, H19 was associated with stem cell phenotype in ALDH1-positive breast cancer; furthermore, H19 regulates breast cancer stem cells (CSC) and is associated with poor prognosis in breast cancer patients, particularly in triple-negative subtype." (PMID 31299871, 2019). "In recent years, lncRNA H19 was identified to be significantly associated with various human cancers including breast cancer, gastric cancer, thyroid cancer, and hepatic carcinoma." (PMID 31016202, 2019). "Many studies have been reported that H19 SNPs were related to cancers risk and prognosis, such as, rs217727 with breast cancer, rs2389698 with gastric cancer, but rs1859168 was reported to reduce the risk of pancreatic cancer." (PMID 29511035, 2018). "MiR-675 is already known to be derived from H19 and has been shown to be implicated in the development of colorectal and breast cancers, while both miR-203a and H19 have been shown to interact with E2F Transcription factor 1 (E2F1)." (PMID 30557328, 2018). "The genetic variants of H19 have been identified to be associated with the susceptibility to breast cancer, bladder cancer, gastric cancer, and colorectal cancer." (PMID 29844862, 2018). "In 2005, H19 was reported to be associated with breast cancer (DO:1612), bladder cancer (DO:11054) and colon cancer (DO:219)." (PMID 28947982, 2017). "Consecutively, other researches have illustrated that lncRNA H19 was actively associated with the E2F1 (E2F transcription factor 1) to promote the cell-cycle progression of breast cancer cells." (PMID 27911863, 2017). "H19 upregulation has been reported in various cancers, such as bladder-, lung-, esophageal-, cervical-, and breast cancer, whereby it is often associated with poor prognosis." (PMID 27608009, 2016). "The expression of H19 in healthy tissues as well as breast adenocarcinomas tissues can further be associated with breast cancer gene and the enhancement in tumorigenic properties of breast cancer cells can be studied." (PMID 30159409, 2016). "First, although the role of H19 in multiple diseases has been reported, this is the first study investigating genetic variation of H19 in relation to breast cancer susceptibility." (PMID 26886624, 2016). "The associations between the H19 SNPs and breast cancer risk were investigated by molecular epidemiology." (PMID 26886624, 2016). "Three articles reported the effects of H19 polymorphisms in breast cancer, two reported in bladder cancer, two in ovarian cancer, one in gastric cancer, one in lung cancer and one in colorectal cancer." (PMID 27732938, 2016). "In this study, we established H19/miR-675 ectopic expression models of MDA-MB-231 breast cancer cells to further investigate the underlying mechanisms of H19 oncogenic action." (PMID 26353930, 2015). "In accordance with studies examining bladder carcinoma, several investigations have also implicated H19 in breast cancer metastasis, where its expression in epithelial cells localized at the epithelial/mesenchymal boundary has been linked to a poor prognosis." (PMID 25101115, 2014).
breast cancer (continued). "In terms of genetic polymorphisms, the H19 SNP rs2839698 variant has been significantly associated with an increased risk of hepatocellular carcinoma 39, and the H19 SNP rs217727 has been linked to a higher risk of breast cancer development." (PMID 39898248, 2025). "Consistently, plasma H19 levels were found to decrease significantly after surgery, and they have been significantly correlated with ER, PR, Her-2, and lymph node metastasis, indicating the potential use of H19 as a diagnostic and monitoring biomarker for breast cancer." (PMID 38505593, 2024). "Additionally, H19 has been implicated in cervical and breast cancers, where it influences cell proliferation, invasion, and immune evasion." (PMID 38166752, 2024). "LincRNA H19 and miR-675 are also promising as new diagnostic markers for breast cancer." (PMID 39267845, 2024). "New studies have found that H19, an imprinted gene associated with the occurrence and development of various tumors, may also be one of the risk factors for breast cancer." (PMID 39267845, 2024). "It was observed that H19 expression was associated with the histological grade of breast cancer." (PMID 37298108, 2023). "Similarly, the over-expression of H19 has also been confirmed as an underlying therapeutic target in paclitaxel-resistant breast cancer cell subline." (PMID 36246634, 2022). "The “T” allele at H19 rs2839698 was reported to be associated with bladder cancer, renal cell carcinoma, ovarian cancer, hepatoblastoma, hepatoma cell carcinoma, gastric cancer, colorectal cancer, and breast cancer." (PMID 33800276, 2021). "Moreover, H19 is associated with the occurrence of various malignant tumours, such as breast cancer, bladder cancer and gastric cancer." (PMID 33236528, 2021). "Previous studies have shown that H19 is associated with the pathogenesis of breast cancer." (PMID 34977037, 2021). "Interestingly, a recent study demonstrated that H19 is associated with chemotherapeutic resistance in breast cancer via the PI3K/Akt signaling pathway." (PMID 34977037, 2021). "Emerging studies have consistently demonstrated that genetic polymorphisms in H19 gene are associated with the risk or prognosis of various cancers, including gastric cancer, colorectal cancer, bladder cancer and breast cancer." (PMID 32509581, 2020). "Our study suggests that the lncRNA H19 could be a potential marker for breast cancer diagnosis, prognosis and risk management." (PMID 33335214, 2020). "It would be relevant to investigate if these signaling pathways are similarly activated in breast cancer cells, as a better knowledge of the molecular determinants associated with the H19 and miR-675 phenotypes in breast cancer progression would provide new therapeutic opportunities." (PMID 32610610, 2020). "In the case of endocrine therapy-resistant cancer, H19 expression is linked to increased ERα expression; therefore, downregulating H19 can provide an alternative treatment for therapy-resistant cells with ER+ breast cancer." (PMID 32466143, 2020). "It has been observed that the rs3741219, rs217727, and rs2839698 polymorphisms of H19 were significantly associated with increased risk of breast cancer, while the rs3741216 was significantly contributed with reduced risk of BC among a southeast sub population of Iranian patients." (PMID 31956395, 2020). "Indeed, H19 has already been associated with stemness in breast cancer, in part by favoring symmetric division." (PMID 32610610, 2020). "Similarly, rs217727 T variant of H19 was significantly correlated with increased risk of breast cancer among Chinese cases." (PMID 31956395, 2020). "LncRNA H19 has been identified to be functionally associated with many biological processes, such as cell proliferation, invasion, and apoptosis of tumors, with its crucial role in tumorigenesis breast cancer has been increasingly recognized." (PMID 32514245, 2020). "In terms of H19 rs217727, it was found to increase the risk of breast cancer." (PMID 31752724, 2019).
breast cancer (continued). "From our results, we speculate that the overexpression of H19 in malignant CSCs of breast cancer contributes to reduction in CD24 expression and causes the invasive phenotype." (PMID 30410672, 2018). "However, the association between the H19 polymorphisms and breast cancer (BC) susceptibility has remained elusive." (PMID 26886624, 2016). "Indeed, H19 expression is high in some cancers, including breast carcinomas, where it is associated with metastasis and the acquisition of EMT traits." (PMID 25774169, 2015). "Thus, reduced expression of H19 or ILF2 might serve as a biomarker for determining breast cancer patients with BRCA1 deficiency or low BRCA1 for consideration for use of PARP inhibitors for adjuvant therapy." (PMID 37298108, 2023). "Consequently, H19 is considered a breast cancer diagnostic and prognostic marker." (PMID 35328609, 2022). "Besides, H19 mutation may produce antisense RNA 91H accumulating in breast cancer cells and regulate the expression of insulin growth factor 2 (IGF2), thereby affecting oncogene and tumor suppressor gene expression." (PMID 36588790, 2022). "It has been shown that the expression of the H19 gene is much higher in breast cancer tissues than in healthy tissues." (PMID 41459628, 2026). "On the other hand, H19 can promote breast cancer cell proliferation, metastasis, and cell cycle progression by expressing miR-675, interacting with MYC protein, or taking part in the ceRNA regulatory network." (PMID 41614928, 2026). "Curcumin also reduces H19 lncRNA expression, which is associated with resistance in MCF-7 breast cancer cells." (PMID 40352931, 2025). "Another study comparing plasma from breast cancer patients to healthy controls found elevated levels of lincRNAs H19, HOTAIR, and RP11-445H22.4." (PMID 39997609, 2025). "Zhong’s study revealed that serum exosomal levels of H19 were notably elevated in patients with breast cancer, demonstrating a strong correlation with adverse clinical variables." (PMID 40149989, 2025). "Studies have shown that bharangin downregulates the expression of H19 lncRNA in resistant breast cancer cells." (PMID 40352931, 2025). "H19 acts as an oncogene, regulates gene expression and plays a significant role in E2-induced proliferation in breast cancer cells." (PMID 40868070, 2025). "Metformin, a biguanide drug known for its antidiabetic activity, attenuated lncRNA H19 expression in breast cancer cells." (PMID 40176927, 2024). "LncRNAs particularly H19 and hTERT are important biomarkers in breast cancer based on their main roles in glycolysis." (PMID 38773429, 2024). "We can obtain 5 entries, which show that H19 is up-regulated in doxorubicin resistant cells in several diseases, such as breast cancer." (PMID 37953323, 2024). "LncRNA H19 (Long non-coding RNA H19) is known to play a role in breast cancer tumorigenesis and metastasis by influencing the epithelial-mesenchymal transition (EMT)." (PMID 39479021, 2024). "H19 has been shown to have tumorigenic properties in breast cancer, hepatocellular carcinoma (HCC), and ovarian carcinoma." (PMID 39659621, 2024). "A noteworthy example includes its ability to downregulate lncRNA H19, an action that can suppress the resistance of breast cancer cells to tamoxifen." (PMID 38505593, 2024). "This significant upregulation suggests a pivotal role for LincRNA H19 as an oncogene in the progression and prognosis of breast cancer." (PMID 39267845, 2024). "H19 plays a central role in inducing chemoresistance in breast cancer, lung cancer, glioma, liver cancer, and other malignancies." (PMID 38794196, 2024). "This molecular function of EV-contained H19 has also physiological consequences for the recipient breast cancer cells as it promotes their growth and resistance to paclitaxel." (PMID 39585046, 2024). "Numerous studies have examined the role of lncRNA H19 as an oncogenic lncRNA in breast cancer progression." (PMID 38691224, 2024).